NQO1 (NAD(P)H quinone dehydrogenase 1)
Diseases named in the same sentence as NQO1 in open-access papers (continued):
Sharing a sentence is not in itself a finding about the gene and the disease.
neuroblastoma (17 papers, 2011 to 2024). Neuroblastoma (NB) is the most common solid, extracranial childhood tumor. "In agreement with this, a previous study that first described the role of DPP3 in modulating NRF2 response in neuroblastoma cells also demonstrated NQO1 as a target of this mechanism." (PMID 37531267, 2023). "Previously, it was demonstrated that Nrf2 is a critical transcription factor for both basal and induced levels of NQO1 expression in IMR-32 human neuroblastoma cells." (PMID 27456681, 2016). "In this respect, MQ has been shown to neutralize free radical activity in SH-SY5Y neuroblastoma cells, but only when cells were pretreated with the NQO1 inducer, sulforaphane." (PMID 23441223, 2013). "Here we used human neuroblastoma cells with low or high levels of the PMRS enzyme NADH-quinone oxidoreductase 1 (NQO1) to investigate how the PMRS modulates mitochondrial functions and cell survival." (PMID 23874855, 2013). "To further characterize the effects of NQO1 on bioenergetics we measured levels of NAD+ and NADH in neuroblastoma cells with low or elevated levels of NQO1." (PMID 23874855, 2013). "In this study, we used human neuroblastoma cells with low or high NQO1 levels and assessed several mitochondrial functions in the absence or presence of mitochondrial inhibitors." (PMID 23874855, 2013). "We found that overexpression of NQO1 prevents apoptosis of neuroblastoma cells which suggests that inhibition of NQO1 would enhance death of these cells." (PMID 23874855, 2013). "We found that human neuroblastoma cells overexpressing NQO1 were relatively resistant to being killed by mitochondrial toxins as indicated by reduced PARP cleavage, cell shrinkage and chromatin condensation." (PMID 23874855, 2013). "Similarly, NQO1 was observed to undergo polyubiquitination and then proteasome degradation, compromising its antioxidant action, in neuroblastoma cells." (PMID 34439544, 2021). "Similar results were observed for NQO-1 expression levels in neuroblastoma cells." (PMID 34452164, 2021). "Indeed, we found that neuroblastoma cells overexpressing NQO1 were more resistant to being killed by the mitochondrial toxins rotenone and antimycin A." (PMID 23874855, 2013). "Finally, our findings suggest that NQO1 is a target for the development of therapeutic interventions for neuroblastoma, and possibly other types of neural tumors." (PMID 23874855, 2013). "Similarly, human neuroblastoma cells (SH-SY5Y) showed low NQO1 expression (3.7±0.3%) as well as ATP rescue capacity (−0.8±0.3%)." (PMID 21483849, 2011). "In the present study we show that CBR-470-1 activates the Nrf2 cascade in SH-SY5Y neuroblastoma cells, causing disassociation of the Keap1-Nrf2 complex, cytosol Nrf2 protein stabilization and nuclear translocation, followed by increased expression of Nrf2 pathway genes (HMOX1, NQO1 and SOD1)." (PMID 32649311, 2020). "However, we found that overexpression of NQO1 results in decreased mitochondrial ROS levels in human neuroblastoma cells, even though they produce more ATP via increased activity of mitochondrial electron transport chain complexes compared to control cells under normal culture conditions." (PMID 23874855, 2013). "In a recent study, we presented data on the capability of compound 1 to induce NRF2 in the human SH-SY5Y neuroblastoma cell line and to promote the endogenous upregulation of NRF2-dependent defensive genes such as NQO1 and HO-1." (PMID 33003644, 2020). "DHPA, an antioxidant and anti-inflammatory substance, inhibited Aβ1-42/Cu2+/ascorbic acid-induced oxidative damages by regulating mitochondrial apoptosis in human neuroblastoma SH-SY5Y cells, inducing the KEAP1/Nrf2/HO-1 signaling axis and enhancing the expression of NQO1." (PMID 38167027, 2024).
neuroblastoma (continued). "For example, research on carrot-derived EVs has demonstrated their ability to restore the Nrf2 pathway and increase the expression of antioxidant proteins, such as HO-1 and NQO-1, in H9C2 cardiomyocytes and SH-SY5Y neuroblastoma cells, thereby regulating intracellular ROS levels." (PMID 39765803, 2024). "It has been reported that overexpression of DPP3 could potently activate the ARE in neuroblastoma cells (IMR-32 cells), leading to increased expression levels of NAD(P)H:quinone oxidoreductase 1 (NQO1), a phase II detoxifying enzyme regulated by ARE." (PMID 32546481, 2020). "Exposure to some 1,2-NQs и 1,4-NQs provokes human neuroblastoma cell lines SK-N-SH apoptosis in a ROS-dependent pathway, including DNA damage, mitochondrial dysfunction, and resultant caspase 3 and 9 activation together with GSH decrease, proteasome inactivation and NQO1 upregulation." (PMID 38393033, 2024).
asthma (16 papers, 2009 to 2024). "Our findings indicated that CRE effectively protected against OVA-induced inflammation and oxidative stress via upregulation of the Nrf2/HO-1/NQO1 signaling and downregulation of NF-κB phosphorylation in asthma caused by OVA." (PMID 34679759, 2021). "NQO1 Pro187Ser mutation was associated in our study, but was also associated with asthma and exposure to tobacco smoke in a previous study." (PMID 23066387, 2012). "Two haplotypes located in two genes (CAT and NQO1) were associated to asthma before correction when the sample was stratified according to proximity to aluminium industries." (PMID 23066387, 2012). "For example, the two associated genes (CAT and NQO1) have been associated with asthma and tobacco smoke exposures." (PMID 23066387, 2012). "CC carriers of NQO1 rs2917666 living in the same home during follow-up had an increased risk for prevalence (OR = 2.42; 95% CI, 1.19–5.24) and new-onset asthma (OR = 2.89; 95% CI, 1.02–9.46)." (PMID 20049212, 2009). "Findings from this study suggest that genetic polymorphisms in the NQO1 gene are associated with susceptibility to asthma in adults among those exposed to traffic-related air pollution." (PMID 20049212, 2009). "Subjects homozygous for the NQO1 rs291766 C allele were at greater risk (p-value for interaction = 0.04) for developing asthma (OR = 2.02; 95% CI, 1.16–3.73) compared with those with CG/GG genotypes (OR = 1.26; 95% CI, 0.83–1.99)." (PMID 20049212, 2009). "We observed stronger associations between NO2 concentrations and both prevalent and new-onset asthma among subjects homozygous for the most common allele of NQO1 compared with carriers of NQO1 variants." (PMID 20049212, 2009). "In this study, we did not observe significant associations of GSTM1 or GSTP1 polymorphisms with asthma either alone or in combination with NQO1 SNPs." (PMID 20049212, 2009). "The association between modeled NO2 and asthma prevalence was significant for carriers of the most common genotypes of NQO1 rs2917666 [odds ratio (OR) = 1.54; 95% confidence interval (CI), 1.10–2.24], TNFA rs2844484 (OR = 2.02; 95% CI, 1.30–3.27)." (PMID 20049212, 2009). "Genetic polymorphisms in the NQO1 gene are related to asthma susceptibility among persons exposed to local traffic-related air pollution." (PMID 20049212, 2009). "NAD(P)H:quinone oxidoreductase 1 (NQO1), which has a role in oxidative stress, may be related to asthma susceptibility among persons exposed to traffic-related air pollution." (PMID 23584289, 2013). "Studies focusing on the impact of ozone exposure have corroborated that polymorphisms in oxidative stress genes, such as NQO1, GSTM1, and GSTP1, can precipitate respiratory symptoms and elevate the risk of asthma development." (PMID 39316602, 2024). "Based on our findings, LOL effectively attenuated airway inflammation and oxidative stress by suppressing of MAPKs and p65NF-κB activation, and by activating of Nrf-2/HO-1/NQO1 signaling in the OVA-challenged asthma model." (PMID 32605045, 2020). "HTR2C, CYP1B1, CYP19A1, ESR1, ESR2, PDR, and AR are found to be interrelated to hormonal disorders; ABCC1, NQO1, TIMP1, ADRB2, and ALOX5 are associated with asthma." (PMID 29861771, 2018). "These include exposures such as PM10, PM2.5, ozone and NO2 and effects associated with altered asthma outcomes in those with particular single nucleotide polymorphisms in genes such as GSTP1, NQO1 and GSTT1." (PMID 29157272, 2017). "Polymorphisms in genes related to oxidative stress (NQO1, GSTM1, and GSTP1) have been associated with increased risk of asthma." (PMID 24465030, 2014). "Two genes were associated with asthma in the entire sample before correction (CAT and NQO1) and one was associated after correction for multiple analyses (CAT)." (PMID 23066387, 2012).
asthma (continued). "The association between prevalence of asthma and NO2 was significant for subjects homozygous for the major allele of NQO1 rs2917666 (OR = 1.54; 95% CI, 1.10–2.24) and for TNFA rs2844484 (OR = 2.02; 95% CI, 1.30–3.27)." (PMID 20049212, 2009). "Recent research manifested that Divya–Swasari–Kwath could inhibit asthma in mice by increasing the mRNA expression of antioxidant defense gene Nrf-2 and upregulating downstream target genes HO-1 and NQO-1." (PMID 34867926, 2021). "In addition, after including the random effects of center in a generalized mixed model, the interaction of NO2 and NQO1 rs2917666 was still significant for the prevalence of asthma (p-value for interaction = 0.02)." (PMID 20049212, 2009). "A significant interaction was found between NQO1 rs2917666 and NO2 for asthma prevalence (p = 0.02) and new-onset asthma (p = 0.04)." (PMID 20049212, 2009). "For new-onset asthma, the effect of NO2 was significant for the most common genotype of NQO1 rs2917666 (OR = 1.52; 95% CI, 1.09–2.16)." (PMID 20049212, 2009). "We further performed the haplotype analysis for the three SNPs of NQO1 (rs10517, rs1800566, and rs2917666) in relation to NO2 exposure and prevalence of asthma." (PMID 20049212, 2009). "In contrast, no induction of NQO1 or HO-1 was observed in the HDM-stimulated Nrf2−/− mice, which may explain the increased oxidative stress seen in asthma, as the defense mechanism against oxidative stress was disrupted." (PMID 39061887, 2024).
gastric cancer (16 papers, 1999 to 2023). A primary or metastatic malignant neoplasm involving the stomach. "In their study, on stratifying by cancer subgroup, they found significantly increased correlation between two type of cancer (bladder cancer and gastric cancer) and NQO1 polymorphism." (PMID 36338728, 2022). "These authors concluded that the 609C > T polymorphism of the NQO1 gene increases the risk for developing stomach cancer, especially in the Asian population." (PMID 34356648, 2021). "The gastric cancer patients of The Cancer Genome Atlas program were divided into high-risk or low-risk groups according to the survival status, and the patients with a high risk showed a significantly lower NQO1 expression in gastric tumor tissues." (PMID 37188198, 2023). "A retrospective study reported that NQO1 was overexpressed in gastric cancer and associated with poor prognosis, which demonstrates that NQO1 might be a promising biomarker in the prognostic evaluation for gastric cancer patients with adjuvant chemotherapy." (PMID 37188198, 2023). "Notably, the overexpression of NQO1 in gastric cancer was also reported, and the alteration of NQO1 gene C609T polymorphism was associated with increased gastric cancer risk." (PMID 37188198, 2023). "In another study of the Asian population, a relationship between the 609C > T oxidoreductase (NQO1) polymorphism and gastric cancer was found and a significantly increased risk (46%) of gastric cancer (95% CI = 1.20–1.79; p < 0.001) was demonstrated in people with the T allele." (PMID 34356648, 2021). "In this sense, our analysis based on the gene level of NQO1 in gastric cancer was diametrically opposite to Jiang’s report." (PMID 37188198, 2023). "Based on the evidence presented, it can be concluded that our results are consistent with and support the notion that the decreased level of NQO1 in tumor tissues predicts the poor prognosis for gastric cancer patients." (PMID 37188198, 2023). "It is also essential for researchers to conduct more comprehensive studies on the molecular mechanism of NQO1 in gastric cancer and explore its potential as a prognostic and therapeutic target for translation into clinical practice." (PMID 37188198, 2023). "In Jiang’s work, the gastric cancer patients with high NQO1 expression showed poor overall survival probability, suggesting that NQO1 was a tumor promoter." (PMID 37188198, 2023). "Another point worth noting is that Jiang’s report on gastric cancer patients with surgery only showed that the higher-NQO1 patient groups displayed a higher OS rate, which was similar to our findings." (PMID 37188198, 2023). "The consistent results also confirmed that NQO1 gene expression was downregulated in gastric cancer tissues." (PMID 37188198, 2023). "To fully understand the expression of NQO1 in gastric cancer, we analyzed the expression of NQO1 in different tissues by the Human Protein Atlas, Consensus, and Genotype Tissue Expression (GTEx) datasets in the Human Protein Atlas." (PMID 37188198, 2023). "Given the discovery of reduced NQO1 expression in gastric cancer, it is necessary to re-examine the correlation between NQO1 expression and patients’ survival." (PMID 37188198, 2023). "In conclusion, assessing the prognostic value of NQO1 in patients with gastric cancer who have undergone adjuvant chemotherapy is a crucial aspect of clinical practice." (PMID 37188198, 2023). "Considering the opposite results about the expression of NQO1 in gastric tumor tissues, we further analyzed the clinical significance of NQO1 in gastric cancer." (PMID 37188198, 2023). "Our previous study also showed that NQO1 was a significant prognostic or predictive marker in gastric cancer." (PMID 24912939, 2014). "However, some concerns should be discussed, and we also provided some supplementary results about NQO1 in gastric cancer." (PMID 37188198, 2023).
gastric cancer (continued). "The results from the Kaplan–Meier survival analysis tool showed that three transcript isoforms of NQO1 (including 201467_s_at, 201468_s_at, and 210519_s_at) all demonstrated that the gastric cancer patients with a higher expression of NQO1 had a favorable overall survival (OS) probability." (PMID 37188198, 2023). "Another important issue is that Jiang’s work showed that gastric cancer patients with a high NQO1 expression were more sensitive to 5-fluorouracil-based adjuvant chemotherapy, indicating that NQO1 may play a role in chemotherapy sensitization." (PMID 37188198, 2023). "Then, we proposed a question on the expression status of NQO1 in gastric cancer." (PMID 37188198, 2023). "However, the clinical significance of NQO1 was little known, and the full study of NQO1 in gastric cancer is an insightful work." (PMID 37188198, 2023). "However, a further analysis of NQO1 expression in gastric cancer and its correlation with patient prognosis is necessary to fully understand the clinical implications of NQO1." (PMID 37188198, 2023). "Considering other previous reports that NQO1 was overexpressed in gastric tumor tissues than in normal gastric mucosa tissues and the specific expression of NQO1 in stomach tissues, the comprehensive validation of the expression status of NQO1 in gastric cancer is an important work." (PMID 37188198, 2023). "This study focuses on the expression and the clinical significance of NQO1 in gastric cancer, the comprehensive evaluation of NQO1 of which we believe is conducive to an in-depth exploration of clinical value and provides a reference for subsequent basic research and translational applications." (PMID 37188198, 2023). "NQO1 (the NADPH oxidoreductase gene) is linked to various theories of carcinogenesis, particularly rs1800566, which was found to demonstrate a strong association with gastric cancer or hepatocellular and renal carcinoma through changes in redox status inside the cells." (PMID 37763073, 2023). "The total number of included gastric cancer patients was significantly larger than those of some previous reports, and we believe that it could more objectively reflect the clinical significance of NQO1 in gastric cancer." (PMID 37188198, 2023). "Moreover, the evidence suggests that NQO1 may function as a tumor suppressor in the context of gastric cancer." (PMID 37188198, 2023). "In Jiang’s report, NQO1 was expressed in AGS cells, a gastric cancer cell line." (PMID 37188198, 2023). "We evaluated the transcription levels of the genes Nrf2, GCLM, NQO1, and HMOX1 as well as the protein expression levels of these genes in gastric cancer cells to determine whether Nrf2 is involved in the CEP-induced oxidative stress mechanism." (PMID 38086844, 2023). "Of these 12 genes, 7 genes highly expressed in gastric cancer tissues were down-regulated (ITGB5, TYMS, MYB, APOC1, CBX5, PLA2G2A, KIF20A) and 5 low-expressed genes were up-regulated after vorinostat treatment (SCGB2A1, TCN1, CFD, APLP1, NQO1." (PMID 21931799, 2011). "In Jiang’s report, the overexpression of NQO1 in gastric cancer tissues was also not confirmed." (PMID 37188198, 2023). "The treatment of polysaccharides at a high dose of 9.6 g/kg could protect against the precancerous lesions of gastric cancer (PLGC) in rats by activating the Nrf2 pathway and its downstream antioxidant enzymes like heme oxygenase 1 (HO-1) and NAD(P)H: quinone oxidoreductase-1 (NQO-1)." (PMID 36160715, 2022). "Therefore, the remarkable expression in gastric tumor tissues could not support the conclusion of NQO1 overexpression in gastric cancer." (PMID 37188198, 2023).
Parkinson disease (16 papers, 2012 to 2025). A progressive degenerative disorder of the central nervous system characterized by loss of dopamine producing neurons in the substantia nigra and the presence of Lewy bodies in the substantia nigra and locus coeruleus. "Increased levels of antioxidant enzymes such as NQO1, HO-1, catalase, etc., by the Nrf2 pathway provide a major defense against oxidative stress in Parkinson’s and stroke." (PMID 39062165, 2024). "In contrast, NQO1 and peroxiredoxin 6 are strongly expressed in astrocytes in substantia nigra of Parkinson’s disease brain, with more infrequent expression in neurons." (PMID 28820437, 2017). "Nrf2, NQO1, and HO-1, as antioxidative molecules, were always used as biomarkers to detect the drug effects on MI and Parkinson’s disease, for instance, cytoplasm HO-1, cytoplasm NQO1, and nucleus Nrf2 expressions increased both in vivo and in vitro using azafrin after MI." (PMID 35845045, 2022). "Increased NQO1 and HO-1 levels shown in postmortem brain tissues of Parkinson’s disease patients as well as increased nuclear levels of Nrf2 suggest that induction of expression of Nrf2-regulated proteins could be an important survival mechanism." (PMID 30965670, 2019). "Transcript levels of the anti-oxidant NQO1 were significantly elevated in Gaucher disease [0.017 (IQR 0.014–0.019), Mann-Whitney U-test P = 0.012] and Parkinson’s disease with GBA mutation fibroblasts [0.02 (0.016–0.023), P = 0.024] compared with controls [0.01 (IQR 0.007–0.014)]." (PMID 24574503, 2014). "Similarly, Parkinson’s disease patient olfactory neurosphere-derived cells display oxidative stress, decreased glutathione and decreased NQO1 expression, even though Nrf2 levels are maintained, and exhibit an altered response to stimulation by sulforaphane compared to controls." (PMID 28820437, 2017). "NQO1 and HO1 are strongly elevated in Parkinson’s disease brain, an effect restricted to the substantia nigra pars compacta compared to adjacent tissue." (PMID 28820437, 2017). "Also, expression of ARE-driven genes, such as NAD(P)H dehydrogenase, quinone 1 (NQO1) and heme oxygenase (decycling) 1 (HO-1), is increased in brain tissue in a Parkinson’s disease (PD) mouse model, which could be a neuroprotective response mediated by NFE2L2 activation." (PMID 27531979, 2016).